ARIH1 (ariadne RBR E3 ubiquitin protein ligase 1)
Diseases named in the same sentence as ARIH1 in open-access papers (continued):
Sharing a sentence is not in itself a finding about the gene and the disease.
cancer (29 papers, 2019 to 2026). A tumor composed of atypical neoplastic, often pleomorphic cells that invade other tissues. "Dysregulation of ARIH1 (discussed later) has been linked to immune evasion in cancer, where it hampers anti-tumor immune responses and supports tumor growth." (PMID 39851497, 2025). "Loss of the E3 ubiquitin-protein ligase ARIH1 has been associated with cancer escape from anti-tumor immunity." (PMID 37429863, 2023). "In the context of tumorigenesis, ARIH1 upregulation in cancer and an association with the proliferation marker ki67 have been described previously." (PMID 35102251, 2022). "Cancer-associated mutation of ARIH1 compromises ubiquitination of PD-L1." (PMID 33879767, 2021). "To explore the role of ARIH1 in cancer progression, we stably silenced ARIH1 in both SUM159 and Py8119 cells through shRNA KD and CRISPR Cas9 KO, respectively." (PMID 40075632, 2025). "Modulation of cancer immune response by Ariadne family member E3 ligase ARIH1: ARIH1 appears to ubiquitinate PD-L1 in response to GSKα-mediated phosphorylation of PD-L1." (PMID 39851497, 2025). "Recent studies have indicated that ARIH1-mediated mitophagy promotes therapeutic resistance in cancer cells." (PMID 40075632, 2025). "Consistently with BEX2, ARIH1-induced mitophagy has been found to enhance the resistance of cancer cells to chemotherapy-induced cell death." (PMID 37777549, 2023). "Our findings delineate a mechanism that tumors mediate ICB resistance through the loss of ARIH1 and ARIH1-DNA-PKcs-STING signaling and indicate that activating ARIH1 is an effective strategy to improve the efficacy of cancer immunotherapy." (PMID 37429863, 2023). "We compared the protein levels of ARIH1 in six murine cancer cell lines and found that B16-F10 cells had relatively high levels of ARIH1 (ARIH1-High), while 4T1 had relatively low levels of ARIH1 (ARIH1-Low)." (PMID 37429863, 2023). "In cancer, ARIH1 can inhibit the function of drugs on tumor cells by regulating autophagy and can act as a suppressor to inhibit tumor development." (PMID 37005687, 2023). "ARIH1 induce mitophagy in a PRKN-independent manner in cancer cells resulting in cancer cell resistance to anti-cancer therapy." (PMID 37007026, 2023). "A study identified an E3 ubiquitin ligase called ARIH1/HHARI that triggers mitophagy in cancer cells in a PINK1-dependent manner." (PMID 38155968, 2023). "ARIH1 is mainly expressed in pluripotent stem cells and various cancer cells, especially lung cancer cells." (PMID 35534453, 2022). "Still, the presence of RBR E3 ubiquitin-protein ligase 1 (ARIH1) challenges this view because it has been shown to protect cancer cells from chemotherapy-induced death." (PMID 35534453, 2022). "The role of ARIH1 in cancer chemoresistance has been increasingly recognized." (PMID 40075632, 2025). "Interestingly, ARIH1 expression in cancer cells allows for apoptosis avoidance against chemotoxicity, suggesting that ARIH1-mediated mitophagy contributes to a chemotherapy resistance mechanism." (PMID 34688664, 2021). "In addition to completely PINK1/parkin-independent mitophagy pathways, the ariadne-1 homolog in humans (ARIH1) promotes mitophagy in cancer cells independently of parkin but in a PINK1-dependent manner." (PMID 34688664, 2021). "Together, our results suggest ARIH1 is the E3 ligase for PD-L1, which could lead to the development of therapeutic strategies to overcome immunotherapy resistance in cancers and enhance checkpoint blockade therapy efficacy." (PMID 33879767, 2021). "The mechanisms that result in decreased ARIH1 expression levels in cancer remain to be elucidated." (PMID 33879767, 2021). "We recently established that ARIH1 was a key regulator of mitophagy in cancer cells and that its knock-down could sensitize cells towards chemotherapy-induced apoptosis." (PMID 33288741, 2020). "However, the understanding of how ARIH1 influence cancer development is limited." (PMID 40285603, 2025).
cancer (continued). "Indeed, here we present data that suggests that ARIH1 acts as a key player in cancer progression." (PMID 35102251, 2022). "Considering these findings, further research is urgently needed to elucidate the roles of ARIH1, SIAH2, UBR5, and WWP2 in modulating mitophagy, mitochondrial homeostasis, and drug resistance in cancer." (PMID 40004017, 2025). "The identification of hnRNP-E1 as a candidate substrate of ARIH1 led to the characterization of a novel function for this ubiquitin ligase in EMT induction and cancer progression." (PMID 35102251, 2022). "Overall, these data suggest that ARIH1 regulates EMT induction, stemness and cancer progression through the coordinated control of multiple downstream targets." (PMID 35102251, 2022). "Overall, these data indicate that hnRNP E1 contributes to ARIH1’s function in EMT, stemness and cancer progression, however, the degree of contribution appears to be cell type dependent." (PMID 35102251, 2022). "In cancer cells, the E3 ubiquitin ligase ARIH1/HHARI induces PINK1-dependent mitophagy through a mechanism independent of Parkin." (PMID 35203359, 2022). "Previous studies have reported that RNF14, RNF31, RNF144B, RNF216 and ARIH1 mainly play carcinogenic roles, while ARIH2 and PARK2 generally play anticancer roles in malignant tumors." (PMID 35732617, 2022). "Here, we demonstrate that ARIH1 is upregulated during TGFβ-induced EMT and this E3 ubiquitin ligase plays a novel role in the mesenchymal transition and cancer progression." (PMID 35102251, 2022). "ARIH1 is a component of the CRL system and regulates cancer progression and xenophagy of cytosolic bacteria." (PMID 36217001, 2022). "Several E3 ligases trigger mitophagy in cancer cells in a Pink1-dependent but Parkin-independent manner, such as Ariadne RBR E3 Ub protein ligase 1 (ARIH1) and seven in absentia homolog 1 (SIAH-1)." (PMID 36289190, 2022). "Our work suggests that GSK3α- and ARIH1-activating agents, as well as EGFR inhibitors, are likely to stimulate anti-tumor immunity and therefore enhance existing cancer therapies by triggering the PD-L1 degradation pathway this work delineates." (PMID 33879767, 2021). "ARIH1 is an E3 ligase that appears to act in concert with cullin-RING E3 ligases to be the main mediator of mitophagy in Parkin-downregulated cancer cells." (PMID 34897410, 2021). "In cancer cells, where ARIH1 (Ariadne RBR E3 Ub protein ligase 1) is highly expressed and Parkin is often downregulated, the Ub ligase activity of ARIH1 promotes mitophagy in a PINK1-dependent manner, contributing to chemotherapy resistance." (PMID 35011593, 2021). "We hypothesize that ARIH1’s role in EMT and cancer progression is a result of modulating several targets in a coordinated manner." (PMID 35102251, 2022). "Overall, further research is warranted to interrogate ARIH1 expression regulation under both physiological and pathological conditions and to delineate the mechanisms through which this ligase functions during EMT and cancer progression." (PMID 35102251, 2022). "Consistent with this hypothesis, in ARIH1 miniTurboID experiments we detect several interacting proteins with a role in EMT modulation and cancer progression, including TJP1 (ZO1), CYLD, and UPF1." (PMID 35102251, 2022). "The identification of hnRNP E1 as a candidate substrate of this ubiquitin ligase is an exciting area of research that may define a novel function for ARIH1 in EMT induction and cancer progression." (PMID 35102251, 2022). "Whereas immunocompetent mice are able to reject cancer cell lines overexpressing the ARIH1 E3 ligase, immunocompromised mice are not, reinforcing the crucial role of ARIH1-ubiquitin-dependent pathways in anti-tumor immunity." (PMID 34639141, 2021). "Our results delineate a mechanism of PD-L1 degradation and cancer escape from immunity via EGFR-GSK3α-ARIH1 signaling and suggest GSK3α and ARIH1 might be potential drug targets to boost anti-tumor immunity and enhance immunotherapies." (PMID 33879767, 2021).
cancer (continued). "Whereas parkin is widely expressed in neuronal cells and absent in many cancer cell lines, ARIH1 is highly expressed in various cancer cells." (PMID 34688664, 2021). "As ARIH1’s function in a cancer setting has not been adequately explored, the identification of novel interactors of this ligase may lead to significant advancements in our understanding of this protein’s role in tumorigenesis." (PMID 35102251, 2022). "Finally, we utilized miniTurboID proximity labeling to identify novel ARIH1 interactors that may contribute to ARIH1’s function in EMT induction and cancer progression." (PMID 35102251, 2022). "ARIH1 is an E3 ubiquitin ligase widely expressed in numerous cancer cells that has also been demonstrated to ubiquitinate mitochondria to induce mitophagy in a PINK1- but not Parkin-dependent manner, which may contribute to chemotherapeutic resistance during cancer treatment." (PMID 32235615, 2020). "Notably, an E3 ubiquitin ligase ARIH1 highly expressed in cancer cells could trigger mitophagy in a PINK1-dependent and Parkin-defective way; this countered the chemotherapy-induced cell death in breast cancer and lung adenocarcinomas, eventually resulting in cancer cell resistance." (PMID 32587855, 2020). "However, ARIH1’s function in EMT induction and cancer progression has not been defined." (PMID 35102251, 2022).
tumor (18 papers, 2009 to 2026). "This stabilization of ARIH1 led to increased infiltration of tumor-associated cytotoxic T cells, reduced tumor growth, and enhanced anti-PD-L1 response." (PMID 39851497, 2025). "Compared to the findings of Elodie's study, both our results demonstrate that in various tumor cell types, ARIH1 regulates mitochondrial molecules, thereby influencing mitochondrial function." (PMID 40285603, 2025). "Xenograft tumor models and liver metastasis models were developed to investigate the in vivo effects of ARIH1." (PMID 40285603, 2025). "We found that ARIH1 showed higher expression levels in tumor tissue, consistent with the results obtained from the TCGA database." (PMID 40285603, 2025). "The tumor volume and weight markedly increased when ARIH1 was overexpressed; however, inhibition of ARIH1 revealed an inverse effect." (PMID 40285603, 2025). "Previous cellular studies found that ARIH1, as a regulator of mitophagy, helped tumor cells maintain mitochondrial homeostasis and overcome sensitivity to chemotherapy." (PMID 37429863, 2023). "The survival of Arih1-WT-OE tumor-bearing mice treated with anti-PD-L1 was also significantly prolonged compared to the wild-type group treated with lgG or anti-PD-L1." (PMID 37429863, 2023). "Analysis of animal and clinical data shows a positive correlation between ARIH1 expression and checkpoint blockade response in multiple tumors, suggesting that ARIH1 is a promising target for tumor immunotherapy." (PMID 37429863, 2023). "Gene set enrichment analysis (GSEA) revealed that the gene sets related to STING pathway were upregulated in Arih1-WT-OE cells compared to Arih1-C355S-OE cells, indicating that Arih1-WT-OE in tumor cells triggers the activation of the STING pathway." (PMID 37429863, 2023). "In combination with our findings, we found that ARIH1, as a tumor suppressor, participates in immune system-mediated tumor killing in vivo." (PMID 37429863, 2023). "Arih1 overexpression promotes cytotoxic T cell infiltration, inhibits tumor growth, and potentiates PD-L1 blockade." (PMID 37429863, 2023). "Together, these observations indicate that ARIH1-WT-OE promotes PD-L1 blockade-mediated anti-tumor immunity in a STING-dependent manner." (PMID 37429863, 2023). "Collectively, these data suggest that ARIH1-WT-OE enhances PD-L1 blockade-induced anti-tumor immunity dependent on its enzymatic activity." (PMID 37429863, 2023). "We discovered that tumor growth in the Arih1-WT-OE group was significantly decreased compared with wild-type control, and treating with anti-PD-L1 led to a further decrease in tumor burden and achieved complete regression." (PMID 37429863, 2023). "Collectively, our data indicate that ACY738 is a promising molecule and drug candidate to boost anti-tumor immunity and enhances PD-L1 blockade therapy by increasing the protein levels of ARIH1." (PMID 37429863, 2023). "Like our findings in SUM159 ARIH1 KD cells, xenograft injection of LM2 ARIH1 KD cells into the mammary fat pad of NOD-SCID mice resulted in significantly reduced tumor formation and the loss of lung metastases." (PMID 35102251, 2022). "We observed an increase in tumor volume and weight in xenografts from ARIH1 KD cells silenced for hnRNP E1, with hnRNP E1−/− cells (clone 52) leading to increased tumor volume when compared to hnRNP E1+/− cells (clone 50)." (PMID 35102251, 2022). "Taken together, our data indicate that ARIH1 plays a role in promoting anti-tumor immunity, and that ES-072 is a promising agent to boost anti-tumor immunity and anti-CTLA4 immune checkpoint blockade immunotherapies." (PMID 33879767, 2021). "The levels of total and activated CD8+ cytotoxic T cells (GzmB+) that infiltrated the tumor microenvironment were significantly increased in the ARIH1-OE group." (PMID 33879767, 2021). "Our tumor xenograft experiments revealed an important function of ARIH1 in promoting anti-tumor immunity." (PMID 33879767, 2021).
tumor (continued). "Therefore, the superior antitumor potency of combining cisplatin with anti-PD-L1 is dependent on ARIH1 expression on tumor cells." (PMID 37429863, 2023). "We found that, in the same type of tumor cells, mice with tumors with relatively high ARIH1 expression (ARIH1-High) were more sensitive to PD-L1 treatment, with substantially reduced tumor growth and higher tumor inhibition rate compared to the group with relatively low ARIH1 expression (ARIH1-Low)." (PMID 37429863, 2023). "Next, we aimed to determine whether the anti-tumor effect of ACY738-enhanced PD-L1 blockade therapy is dependent on ARIH1 or STING." (PMID 37429863, 2023). "We next explored whether ARIH1 expression positively correlated with tumor response to checkpoint blockade therapy in mouse models." (PMID 37429863, 2023). "In addition, we observed a positive correlation between ARIH1 expression and checkpoint blockade response in both mouse models and tumor patients." (PMID 37429863, 2023). "Similar to Sting-knockdown, we observed that treatment with C-176 significantly abrogated the anti-tumor effects of PD-L1 blockade therapy in Arih1-WT-OE tumors, together with decreased CD8+ and GzmB+CD8+ T cell infiltration, and reduced expression of ISG genes." (PMID 37429863, 2023). "To test whether ARIH1 is required for the anti-tumor effects of cisplatin-enhanced PD-L1 blockade therapy, we tested the therapeutic efficacy against a subcutaneously tumor model established with Arih1-knockdown 4T1 cells." (PMID 37429863, 2023). "In addition, we performed single-cell sorting of the same type of tumor cells (4T1 and E0771) and selected monoclonal cells with relatively high and low ARIH1 protein levels, respectively, to test their response to PD-L1 blockade." (PMID 37429863, 2023). "Consistently, Arih1-C355S-OE tumors treated with anti-PD-L1 did not cause the accumulation of tumor-infiltrating CD8+ and GzmB+CD8+ T cells." (PMID 37429863, 2023). "It is of great interest to examine whether ARIH1 also exerts anti-tumor activity through promoting ISGylation and activation of cGAS." (PMID 36217001, 2022). "ARIH1 staining was observed in both the cytoplasm and nucleus of tumor cells and a significant increase in stain intensity was observed in lung metastases when compared to primary tumor." (PMID 35102251, 2022). "However, we observed a dramatically suppressed tumor growth in the ARIH1-OE group in immunocompetent BALB/c mice, the majority of which exhibited a complete tumor regression." (PMID 33879767, 2021). "We identified ARIH1 as a promoter of anti-tumor immunity via induction of PD-L1 degradation." (PMID 33879767, 2021). "In xenograft tumor models, SW480 cells, stably transfected with vector or ARIH1‐oe, or DLD‐1 and HCT116 cells transfected with shNC or shARIH1‐1 were injected into the nude mice subcutaneously." (PMID 40285603, 2025). "Immunohistochemistry (IHC) analysis revealed high ARIH1 expression in CRC tissues, with a significantly higher H‐score in tumor tissues." (PMID 40285603, 2025). "In this study, we uncover that ARIH1 regulates DNA-PKcs ubiquitination and degradation, thereby activating the intrinsic STING pathway in tumor cells to promote anti-tumor immunity." (PMID 37429863, 2023). "Here the authors show that ARIH1 mediated ubiquitination and degradation of DNA-PKcs trigger activation of STING pathway in tumor cells, sensitizing tumors to immune checkpoint blockade." (PMID 37429863, 2023). "Our study revealed that Arih1 overexpression in the 4T1 TNBC model, when combined with PD-L1 blockade, displayed complete tumor regression and led to a substantial survival benefit, which was mediated via STING activation." (PMID 37429863, 2023). "We found that compared with normal tissues, tumor tissues expressed elevated protein levels of DNA-PKcs, together with low CD8 and ARIH1." (PMID 37429863, 2023). "Tumor models revealed that ACY738, a identified inducer of ARIH1, enhanced the efficacy of PD-L1 blockade." (PMID 37429863, 2023).
tumor (continued). "Using an ICB-insensitive tumor model, here we discover cisplatin enhances the anti-tumor effect of PD-L1 blockade and upregulates the expression of Ariadne RBR E3 ubiquitin-protein ligase 1 (ARIH1) in tumors." (PMID 37429863, 2023). "In the presence of the immune system, ARIH1 can alter the immune microenvironment of the tumor by stimulating the STING pathway, thereby activating immune system-mediated tumor killing." (PMID 37429863, 2023). "Furthermore, cisplatin contributes to the recruitment and activation of CTLs by upregulating Ariadne RBR E3 ubiquitin protein ligase 1 (ARIH1), chemokine ligand 20 (CCL20) and IL-1β in the tumor tissues." (PMID 39757995, 2025). "Treating Arih1-C355S-OE tumors with anti-PD-L1 showed no reduction in tumor growth or significant survival benefit." (PMID 37429863, 2023). "A subgroup of mice injected with ARIH1 KD cells were monitored for tumor burden past this time point, with no palpable tumors observed at 12 weeks." (PMID 35102251, 2022). "Xenograft injection of two ARIH1 shRNA clones into the mammary fat pad of NOD-SCID mice resulted in no tumors observed at 7 weeks, at which point mice injected with scrambled control cells had reached a maximum tumor burden of 2000 mm3." (PMID 35102251, 2022). "Overexpression of ARIH1 suppresses tumor growth and promotes cytotoxic T cell activation in wild-type, but not in immunocompromised mice, highlighting the role of ARIH1 in anti-tumor immunity." (PMID 33879767, 2021). "The role of ARIH1 in PD-L1 degradation or anti-tumor immunity is not known." (PMID 33879767, 2021). "However, it is unclear whether ARIH1 regulates tumor immunity by participating in other pathways rather than PD-L1 degradation." (PMID 37429863, 2023). "In contrast to ARIH1 silenced cells, xenograft injection of control and ARIH1 ORF SUM159 cells resulted in no significant change in tumor burden between groups, consistent with our mammosphere assays performed in vitro." (PMID 35102251, 2022). "In the absence of the immune system, ARIH1 may maintain normal tumor growth through mitophagy, but ARIH1 can also activate the STING pathway, which may not affect tumor growth." (PMID 37429863, 2023).
infection (1 paper, 2025). The state of being infected such as from the introduction of a foreign agent such as serum, vaccine, antigenic substance or organism. "Additionally, ARIH1 has been observed on Salmonella surfaces prior to LRSAM1 during infection." (PMID 40861495, 2025).